LINC01842 (long independently transcribed non-coding RNA 1842)
Gene: Long non-coding RNA gene on chromosome 19 (14,333,630 to 14,344,487, forward strand). Ensembl gene ENSG00000267147.
Diseases named in the same sentence as LINC01842 in open-access papers:
LINC01842 is named in the same sentence as 1 disease in open-access papers, as found by Europe PMC text mining. Sharing a sentence is not in itself a finding about the gene and the disease.
LINC01842 shares sentences with these, for which no sentence is quoted: lung carcinoma (1 paper).